EPC1 (enhancer of polycomb 1)
Description:
Component of the NuA4 histone acetyltransferase (HAT) complex, a multiprotein complex involved in transcriptional activation of select genes principally by acetylation of nucleosomal histones H4 and H2A. The NuA4 complex plays a direct role in repair of DNA double-strand breaks (DSBs) by promoting homologous recombination (HR). The NuA4 complex is also required for spermatid development by promoting acetylation of histones: histone acetylation is required for histone replacement during the transition from round to elongating spermatids (By similarity). In the NuA4 complex, EPC1 is required to recruit MBTD1 into the complex.
Synonyms: Epl1
Tractability: Small molecule: a structure with a bound ligand is known. PROTAC: UniProt records ubiquitination sites on it; ubiquitination databases record sites on it; its protein half-life has been measured.
Gene: Protein-coding gene on chromosome 10 (32,267,751 to 32,378,798, reverse strand). Ensembl gene ENSG00000120616.
Subcellular location: Nucleus; Cytoplasm
Subcellular location (Human Protein Atlas): Nucleoplasm; Nuclear bodies; Nucleoli
Pathways (Reactome):
Chromatin organization: HATs acetylate histones
Gene expression (Transcription): Transcriptional Regulation by E2F6
Gene Ontology:
Molecular function: chromatin-protein adaptor activity; enzyme-substrate adaptor activity; protein binding; protein-macromolecule adaptor activity
Biological process: double-strand break repair via homologous recombination; negative regulation of DNA-templated transcription; negative regulation of gene expression, epigenetic; negative regulation of transcription by RNA polymerase II; positive regulation of double-strand break repair via homologous recombination; positive regulation of transcription by RNA polymerase II; regulation of cell cycle; sperm DNA condensation; spermatid development; chromatin organization; DNA-templated transcription; positive regulation of DNA-templated transcription; regulation of apoptotic process; regulation of double-strand break repair; regulation of transcription by RNA polymerase II
Cellular component: NuA4 histone acetyltransferase complex; nuclear body; nuclear membrane; nucleolus; nucleoplasm; nucleosome; nucleus; piccolo histone acetyltransferase complex; site of double-strand break; cytoplasm
Genetic constraint (gnomAD): Loss-of-function variants: 12 observed, 84.99 expected, observed/expected ratio (o/e) 0.14, 90% interval 0.089 to 0.23. The upper end of that interval is the gene's LOEUF score, 0.23, which puts it in group 1 of 6, group 1 being the genes least tolerant of losing a copy. Missense variants: 708 observed, 1,001.2 expected, observed/expected ratio (o/e) 0.71, 90% interval 0.66 to 0.75. Synonymous variants: 349 observed, 374.63 expected, observed/expected ratio (o/e) 0.93, 90% interval 0.85 to 1.02.
Homologues: Orthologues: chimpanzee EPC1 (100% identical), macaque EPC1 (99% identical), rabbit EPC1 (98% identical), dog EPC1 (98% identical), pig EPC1 (94% identical), rat Epc1 (94% identical), mouse Epc1 (93% identical), guinea pig EPC1 (91% identical), tropical clawed frog epc1 (85% identical), Drosophila melanogaster E(Pc) (43% identical), Caenorhabditis elegans epc-1 (28% identical). Paralogues in human: EPC2 (54% identical).
Diseases named in the same sentence as EPC1 in open-access papers:
EPC1 is named in the same sentence as 27 diseases in open-access papers, as found by Europe PMC text mining. Sharing a sentence is not in itself a finding about the gene and the disease. The quoted sentences say what the papers report.
acute myeloid leukemia (4 papers, 2021 to 2025). Acute myeloid leukemia (AML) is a group of neoplasms arising from precursor cells committed to the myeloid cell-line differentiation. "In particular, EPC1 has been reported to sustain the oncogenic potential of the leukemic stem cells in MLL-rearranged acute myeloid leukemia and SET2D has been recently implicated in safeguarding the genomic integrity of MLL-rearranged leukemias." (PMID 34304246, 2022). "In addition, EPC1 is associated with acute myeloid leukemia (AML), where it may maintain its carcinogenic potential by inhibiting MYC accumulation and the apoptosis of AML cells." (PMID 40241795, 2025). "Also, it has been reported that EPC1 acts as an oncogene in some types of cancer, such as acute myeloid leukemia (AML), since its suppression triggered apoptosis in cell lines." (PMID 33986977, 2021). "EPC1 and EPC2 are also related to acute myeloid leukemia (AML), which can directly or indirectly suppress the accumulation of MYC and apoptosis of AML cells, thereby maintaining oncogenic potential." (PMID 38439957, 2024).
endometrial stromal sarcoma (4 papers, 2020 to 2022). "According to previous reports, abnormal EPC1 was present in both endometrial stromal sarcoma and ossifying fibromyxoid tumors, whereas EPC1 silencing inhibited lung cancer cell proliferation and tumor growth." (PMID 36158885, 2022). "EPC1 is found fused to PHF1 in endometrial stromal sarcomas and ossifying fibromyxoid tumors, and the present study also identified the EPC1-PHF1 fusion in the round cell sarcoma case #28." (PMID 32825119, 2020). "EPC1 anomalies may be involved in ossifying fibromyxoid tumors, endometrial stromal sarcoma, pancreatic cancer, and nasopharyngeal carcinoma (NPC)." (PMID 36158885, 2022). "Intriguingly, besides AML-related ZM fusion, aberrant chromosomal rearrangements detected in endometrial stromal sarcoma patients recurrently target components of NuA4/TIP60 complex such as EP400, EPC1, EPC2, MEAF6 and MBTD146–50." (PMID 33594072, 2021).
myeloma (2 papers, 2013 to 2015). "EZH2 and EPC1 are two polycomb-related genes upregulated in the myeloma SP." (PMID 23469177, 2013). "It is thus plausible that interaction between EPC1 and EZH2 within myeloma SP cells contributes to their proliferation as well as to cancer stem cell maintenance." (PMID 23469177, 2013).
cyst (1 paper, 2017). A sac-like closed membranous structure that may be empty or contain fluid or amorphous material. "The expression of EPC1 in the irradiated cyst wall decreased and was intermittently expressed in the part near the damaged germinal layer." (PMID 28464914, 2017). "This indicates that EPC1 expressed in the part near the germinal layer surface and was sensitive to cyst activity." (PMID 28464914, 2017). "Our results indicate that EPC1 was mainly continuously and linearly distributed along the germinal layer of the non-irradiated normal cyst wall, and intermittently expressed along the germinal layer of the irradiated cyst wall." (PMID 28464914, 2017).
nasopharyngeal carcinoma (1 paper, 2022). A carcinoma arising from the nasopharyngeal epithelium. "An enhancer of polycomb homolog 1 (EPC1) was found to play a procancer role in nasopharyngeal carcinoma (NPC), but its role in HNSCC with strong heterogeneity is still unclear." (PMID 36158885, 2022). "Additionally, EPC1 has been correlated with patient prognosis in microarray screenings of nasopharyngeal cancer." (PMID 36158885, 2022).
osteosarcoma (1 paper, 2024). A usually aggressive malignant bone-forming mesenchymal neoplasm, predominantly affecting adolescents and young adults. "EPC1 and EPC2, the components of the EP400 and Tip60-EP400 complexes, have been reported to activate gene expression by stimulating H3.3 deposition into promoters and enhancers in U2OS human osteosarcoma cells." (PMID 38439957, 2024).
Stroke (1 paper, 2025). Sudden impairment of blood flow to a part of the brain due to occlusion or rupture of an artery to the brain. "Further studies are planned to explore the therapeutic value of eEPC2-exos alone or in combination therapy with EPC1-exos for treating stroke and other degenerative conditions." (PMID 39829810, 2025).
tumor (9 papers, 2012 to 2026). "Silencing EPC1 in A549 NSCLC cells led to decreased cell proliferation and tumor growth in vitro and in vivo, suggesting EPC1 as a potential therapeutic target." (PMID 40428391, 2025). "Dimensionality reduction and clustering further divided these tumor cells into nine subtypes (Epc1–Epc9), each with distinct gene expression profile." (PMID 40260248, 2025). "After adjusting for tumor purity, 6 kinds of EPC1-related immune cells were screened out from the HNSCC samples under the restriction condition that one of three sample types reached |rho| > 0.3 and P < 0.05." (PMID 36158885, 2022). "In contrast, lnc-EPC1-4 overexpression inhibited cell proliferation and induced cell apoptosis, indicating that it functions as a tumor suppressor gene." (PMID 32554864, 2020). "EPC1-related immune cells, such as macrophage, B cells, and T cells, may play a role in controlling tumor growth." (PMID 36158885, 2022). "The identification so far of four chimeric transcripts in HG‐ESS—YWHAE/NUTM2A/B, ZC3H7B/BCOR, EPC1/SUZ12, and EPC1/BCOR‐is evidence of genetic heterogeneity also within this tumor subgroup." (PMID 33099834, 2021). "Integration of PBMC and tumor profiles identified STEAP4, EPC1, CLEC1B, and LCN2 as shared DEGs." (PMID 41909879, 2026). "Collectively, these findings highlight consistent transcriptional alterations in PBMCs and tumor tissues and suggest that STEAP4, EPC1, and CLEC1B may serve as potential non-invasive biomarkers with diagnostic and prognostic relevance in HCC." (PMID 41909879, 2026).
cancer (6 papers, 2013 to 2024). A tumor composed of atypical neoplastic, often pleomorphic cells that invade other tissues. "This locus contains a number of interesting candidate genes potentially relating to organismal fitness, including Epc1, a transcription factor linked to DNA repair, muscle differentiation and cancer suppression." (PMID 33104702, 2020). "At the protein level, a protein-protein interaction (PPI) network related to EPC1 expression was constructed and found to be involved in HPV infection, endocrine resistance, and multiple cancer pathways." (PMID 36158885, 2022).
EPC1 also shares sentences with these, for which no sentence is quoted: hepatocellular carcinoma (2 papers); infection (2); leukemia (2); Alzheimer disease (1); Autoimmunity (1); breast carcinoma (1); CNS tumors (1); fibromyxoid tumor (1); gastric cancer (1); head and neck squamous cell carcinoma (1); lung carcinoma (1); monoclonal gammopathy (1); neuroblastoma (1); pancreatic cancer (1); peripheral T-cell lymphoma (1); small cell lung carcinoma (1); thrombophilia (1); ulcerative colitis (1).